MYC (MYC proto-oncogene, bHLH transcription factor)
Diseases named in the same sentence as MYC in open-access papers (continued):
Sharing a sentence is not in itself a finding about the gene and the disease.
cancer (continued). "This activation enhances cancer cell migration and invasion through EMT and also activates the proto-oncogene MYC via the ROS/S100A9/MYC signaling axis, promoting tumorigenesis." (PMID 39457673, 2024). "However, when the regulation of c-MYC was disrupted, it might play a significant role in cancer." (PMID 38622518, 2024). "We observed that DNA repair, Oxidative phosphorylation, MYC targets, Bile acid metabolism, and K-Ras signaling had an adverse correlation with the GSVA score of B3GNT5 among the 33 cancer classifications." (PMID 39671359, 2024). "The activity of the Hippo pathway transcription factors substitutes for the activity of oncogenic KRAS G12C in cancer cells treated with inhibitors of KRAS, leading to treatment resistance through activation of the PI3K/AKT cascade and MYC activation." (PMID 39768557, 2024). "Regarding MYC transcriptional regulation, the FGF/FGFR system can strongly influence MYC transcription in several types of cancer." (PMID 39482742, 2024). "Small molecules that stabilize the c-MYC G4 and down-regulate the expression of the c-MYC oncogene have been shown to inhibit the proliferation of cancer cells." (PMID 38203794, 2024). "Cross-referencing these genes with human PPI data revealed distinct groups of interacting proteins that were significantly enriched with cancer-related pathways and processes, including WNT and MYC signaling, RNA splicing, and DNA repair." (PMID 39001492, 2024). "BRD4 is known to activate the transcription of MYC oncogene and various receptor tyrosine kinases (RTK), contributing to cancer cell proliferation and survival signaling." (PMID 38617536, 2024). "In support of the role of CIP2A in the MYC promotion of cancerous transformation, Puustinen and Jӓӓttela reported CIP2A as an oncoprotein that promotes MYC- and MTORC1-mediated cancer transformation by inhibiting the autophagy pathway." (PMID 38994941, 2024). "Previously reported focal CNAs in MSS primary cancers included single-copy and double-copy gains involving CCND1, ERBB2, MYC and KLF5, and deletions of ARID1A, SMAD4 and APC7,31." (PMID 39112709, 2024). "We have previously used PPRHs to target genes related to cancer such as mTOR, BCL-2, MDM2, TOP1, MYC, and HER-2." (PMID 39457457, 2024). "Interestingly, in a lymphomagenesis mouse model entailing MYC constitutive expression, an increase in cell size is observed in pre-transformed B cells, suggesting that MYC-dependent cell enlargement is a process that may be conserved in the development of some mammalian cancers." (PMID 38225354, 2024). "Heatmap showed that substantial activation of oxidative phosphorylation and signaling pathways related to cell proliferation, such as DNA repair, TORC1, MYC and E2F, was correlated with elevated ARPC1A expression in cancer patients." (PMID 39867911, 2024). "Understanding the interplay between MYC dysregulation and KRASi resistance offers insights into co-targeting strategies to potentially enhance treatment efficacy in KRAS-driven cancers." (PMID 39164274, 2024). "And then, to further determine the relationships among ZN706, MYC, and SLC7A11 in the protein level, we performed IHC analysis on cancer tissue chips to examine their expression pattern." (PMID 38862581, 2024).
cancer (continued). "In a different study, in TNBC models including MDA-MB-231 cells, MYC and MCL1 were found to cooperatively promote paclitaxel-resistant cancer stem cells by increasing OXPHOS, reactive oxygen species (ROS) production, and HIF-1α expression." (PMID 38579004, 2024). "The MYC proto-oncogene and bromodomain-containing protein 4 (BRD4) exert their effects by modifying the expression of key cancer-related genes." (PMID 39335515, 2024). "Low levels of let-7b, through the inhibition of MYC, RAS and CCND1, influence the induction of cell proliferation and growth, and thus the progression of cancer." (PMID 38473390, 2024). "Two cancer hallmarks strongly impacted by 1C8 and GPS167 based on the chemogenomic screen and expression/splicing analyses were MYC targets and EMT." (PMID 38753413, 2024). "Due to their frequent alteration and role in tumorigenesis, MYC and RAS emerge as highly appealing targets in cancer therapy." (PMID 39164274, 2024). "To target the pervasive c-MYC expression directly and specifically in human cancers, we have developed an innovative approach based on engineering the genetic codes on the 3′UTR of the MYC gene." (PMID 39123391, 2024). "Results showed a dose-dependent efficacy of MP1 on inhibiting sphere counts/formation and MYC protein expression in both PDX cell lines, suggesting anti-cancer efficacy of MP1 on MB spheres." (PMID 38200580, 2024). "Among these pathways, there were key signaling routes such as KRAS, NOTCH, TGF-β, MYC, and WNT known to play significant roles in cancer progression and therapy resistance." (PMID 39061234, 2024). "To determine the accuracy and LOD of amplifications, we tested reference materials with known copy numbers across six cancer driver genes (EGFR, ERBB2, FGFR3 MET, MYC and MYCN)." (PMID 39682116, 2024). "We found that TAK-981-induced MYC downregulation promoted the activation of STING followed by Stat1 and MHC class I in KRAS-mutant cancer cells." (PMID 39334463, 2024). "Here, we performed a MYC-specific genome-wide CRISPR synthetic-lethality screen and identify nuclear to cytoplasmic transport as a therapeutic vulnerability of MYC-driven cancers." (PMID 38302473, 2024). "In cancer cells, BRD4 regulates the expression of oncogenic gene c-MYC and DNA damage response factors." (PMID 38669046, 2024). "G4s are commonly found in the promoter G-rich region of various proto-oncogenes (e.g., c-MYC, c-KIT), as well as in telomeres (h-TELO) of cancer cells." (PMID 38902227, 2024). "Recently, it has been reported that TERT interacts with various signaling molecules such as NF-κ B, c-MYC, β-catenin, and TCF-4 to increase cancer malignancy and promote cancer progression." (PMID 38927493, 2024). "c-MYC also regulates key transcription factors like SOX2, POU3F2, and OLIG2, driving the reprogramming of cancer stem cells (CSCs) and fueling cancer progression." (PMID 39430761, 2024). "In this present work, we studied the response to individual and combinatorial MYC and KRAS targeting PPRHs in KRAS and MYC-deregulated, dependent, and sensitive prostate PC-3 and pancreatic AsPc-1 cancer cells." (PMID 39457457, 2024). "We identified recognized cancer driver genes (EGFR, MTOR, CCND1, and MYC) within Epi_C1_SPARC and Epi_C6_TCIM subclusters, observing high variability of CNVs in cell proliferation-related genes (TOP2A, MKI67)." (PMID 38720887, 2024). "c-MYC deregulation is more prevalent than N-MYC and L-MYC in human cancer types for both hematological and solid tumors." (PMID 39594704, 2024). "This also revealed that most cancer cells displayed low expression of MCR genes and elevated expression of MYC." (PMID 38877600, 2024). "NO released by nitroprusside induced differentiation in MYC-dependent HL-60 AML cells and apoptosis in NA epithelial cancer cells by suppression of MYB and MYC." (PMID 38835346, 2024).
cancer (continued). "The IL-1β/IL-1 receptor (IL-1R)/β-catenin pathway increases cancer cell growth and metastasis, leading to higher expression of transcription factors, including SNAIL-1 and c-MYC." (PMID 38990306, 2024). "c-MYC plays a key role in CRC tumorigenesis, apoptosis, and glycolytic metabolism, acting as a downstream effector of cancer stems cell (CSC) related signaling pathways like Wnt/β-catenin, Hedgehog, and Notch pathways involved in CSCs regulation in CRC60–63." (PMID 38167453, 2024). "The therapeutic efficacy of CDK9 inhibitors therefore has been reported in MYC-driven and MLL1-rearranged cancers." (PMID 38172923, 2024). "The interaction between SCARB2 and MYC facilitates the acetylation of MYC and enhances its transcriptional activity, leading to increased proliferation of HCC cells, the formation of colonies, and the preservation of cancer stem cell-like properties." (PMID 38997696, 2024). "Stromal fibroblasts from both normal and cancer donors promoted the upregulation of stemness-related genes (ALDH1, AXIN2, CD133, MYC, and SOX9) in EEC organoids." (PMID 39229264, 2024). "Here, we determined that c-MYC is a second cancer-promoting target of LZK in HNSCC and that LZK is required to maintain c-MYC abundance." (PMID 39605563, 2024). "In this review, we elaborate on the regulatory networks between MYC and lncRNAs, using CRC as an exemplary cancer model." (PMID 39075086, 2024). "Our concept and the data presented here indicated that SP1, MYC, and HIF1A were the missing links between miRNAs and cancer stem cells." (PMID 39590335, 2024). "Hence, MYC may be an attractive candidate for effectively controlling tumorigenesis by examination of either protein-protein or protein-small molecule (e.g., ions, MADs, MIZ1, and miRNAs) interactions, to manipulate the balance of MYC expression in cancer cells." (PMID 37450923, 2024). "On the contrary, mir-21 induces the expression of SP1, MYC, and HIF1A and promotes cancer progression via the induction of immune-suppressive mechanisms." (PMID 39590335, 2024). "In various types of cancers, SEs control the expression of prominent tumor-promoting genes such as MYC, TAL1, STAT3 and EGFR, and mediate transcription dysregulation of cancer cells." (PMID 38254188, 2024). "Overexpression of MYC suppresses RCD, such as apoptosis, and promotes cell proliferation, which contributes to cancer development." (PMID 38538696, 2024). "Notably, we discovered that the PI3KCA E542K mutant, whether alone or in combination with exogenous c-MYC, significantly impaired hepatocyte functions and facilitated cancer metabolic reprogramming, highlighting the critical roles of these frequently mutated genes in driving liver neoplasia." (PMID 39336111, 2024). "MYC, a master regulator of cellular metabolism, is the best-known BET protein target and mediates several oncogenic functions of BET proteins in cancer." (PMID 39872506, 2024). "Although the ability of JQ1 to target MYC activity has been most widely studied in the context of cancer, a number of recent studies have investigated the utility of JQ1 in non-cancer settings including contractile tissues." (PMID 38493137, 2024). "Consistent with the effects on the cancer cell growth and survival, knockdown REV-ERBα strongly decreased expression of proteins important for growth, proliferation, and survival including MYC, CDK4, CDK6, CCND2/D3, and BCL2." (PMID 39383000, 2024). "In cancer, upregulated oncoproteins KRAS, MYC, CCNE1, etc. act as primary sources of replicative stress, while also impairing the cell’s ability to adequately respond to such stress." (PMID 38669256, 2024). "For example, CDK9 is critical for the continuous expression of genes producing short-lived mRNAs or proteins, such as MYC and MCL-1 that promote cancer cell survival." (PMID 38326887, 2024).
cancer (continued). "These marker genes represent multiple malignant phenotypes of cancer, including tumorigenesis (EGFR, MYC), cell invasion (ITGB1 and VIM), and angiogenesis (VEGFA), among others." (PMID 38191424, 2024). "For example, EIF4E is often highly expressed in different cancers and can drive the translation of specific mRNAs such as VEGFA, MYC, and TGFB1, which ultimately promote angiogenesis, cell proliferation, and oncogenesis." (PMID 38129098, 2024). "Next, the β-catenin protein translocates to the nucleus, where it interacts with T-cell factors (TCFs) to regulate gene expressions, such as MYC and NRCAM, to accelerate the cell cycle and promote cancer cell metastasis." (PMID 39252305, 2024). "Given the frequent occurrence of deregulations in both MYC and RAS in human cancers, these oncogenes emerge as highly appealing targets for cancer therapy." (PMID 39164274, 2024). "The immunohistochemical analysis revealed significantly higher expression of CD44, MYC, IL17A, CXCL1, FCGR3A, SPP1, and IL1A in cancer tissues, while CXCL12 and CCL5 showed significantly higher expression in adjacent normal tissues." (PMID 39767563, 2024). "CNBP was shown to control transcription of c-MYC and KRAS oncogenes in human cancer by unfolding DNA G-quadruplex structures." (PMID 38635778, 2024). "Our data analysis identified ERBB2 as a direct regulator of key oncogenes such as MYC and BCL2, and tumor suppressors like PTEN in several cancers including PC." (PMID 39409883, 2024). "The MYC OCG was first found in the avian retrovirus genome and activated in cancer cells via proviral integration, gene amplification, and chromosomal translocation." (PMID 38827026, 2024). "Enriched gains spanned known cancer and TGCT drivers including MYC (8q11-q24), EGFR (7p11.2), and BRAF (7q34)." (PMID 39461959, 2024). "This suggests that these miRNAs affect cancers via their activity to either induce or suppress the expression of SP1, MYC, and HIF1A." (PMID 39590335, 2024). "Mechanistically, RUVBL1 was required for MYC to establish oncogenic and immunoevasive gene expression identifying the RUVBL1/2 complex as a druggable vulnerability in MYC-driven cancer." (PMID 38821858, 2024). "M6A‐related genes such as BRD4, MYC, SOCS2, and EGFR are frequently involved in the progression of cancers including LUAD." (PMID 39323079, 2024). "Along with MYCN, other proto-oncogenes such as MYC and KRAS up-regulate components of the spliceosome in cancer, indicating a possible addiction to a hyperactivated spliceosome, and a potential novel therapeutic target." (PMID 38049564, 2024). "MYC is overregulated in three of the five datasets and is related to: 1) cellular senescence along with FOXM1; 2) proteoglycans in cancer along with ELK1; and 3) HCV infection." (PMID 39228892, 2024). "Initially, we planned to test our approach with three crucial genes–PAX5, MYC, and CD79B –- known to play pivotal roles in cancer development and DLBCL growth." (PMID 39469218, 2024). "Various cancer-related pathways including DNA repair, DNA replication, G2/M checkpoint, degradation of ECM, EMT markers, MYC targets, PI3K-AKT-mTOR and TGF-β pathways were enriched." (PMID 38879600, 2024). "Regarding the pro-proliferative MYC gene, several studies found strong transcriptional repression of MYC mediated by DEX, or other glucocorticoids, in various cancer cell lines as well as in vivo." (PMID 36979751, 2023). "Among the different genes within hub CHA regulatory units, MYC and IRF4 are unique as they are transcription factors, immediate early response genes and are involved in cancer." (PMID 37019979, 2023).
cancer (continued). "MYC promoted PCa oncogenic signaling via the PI3K/AKT/mTOR pathway, thereby stimulating massive cancer cell growth." (PMID 37730847, 2023). "We also showed that GLS1 was overexpressed in MYC-driven lung tumors in transgenic mouse models and that inhibition of GLS1 activity led to cancer cell death." (PMID 37512481, 2023). "MUC1-C induces the OCT4, SOX2, KLF4, MYC (OSKM) pluripotency factors in TNBC and other cancer cells." (PMID 37821650, 2023). "We corroborated, using novel ways of correlating absolute SCNA with transcriptomics, that in our organoid models, the correlation was highest for MYC, PIK3CA, and AKT2 reinforcing their putative role as potential targetable cancer drivers." (PMID 37166279, 2023). "Mutations in the KRAS gene and overexpression of protein products of the MYC and ARF6 genes occur frequently in cancer." (PMID 37158894, 2023). "For example, genetic and epigenetic alterations in cancer cells, most notably rearrangements of MLL1 and amplification of MYC, respectively, lead to redirection of P-TEFb to the oncogenes’ loci, stimulating oncogenic transcription programs." (PMID 37811895, 2023). "Subsequently, NUTM1 recruited the histone acetyltransferase EP300 to increase the acetylation of the surrounding chromatin to create a highly acetylated mega-domain, where proliferation genes (such as MYC and TP63) are induced to promote cancer proliferation." (PMID 37049806, 2023). "The analysis revealed a significant correlation between KIFC1 expression and MYC targets, E2F targets, Mitotic spindle, G2M checkpoint, and MTORC1 signaling in the majority of cancer types." (PMID 38112634, 2023). "In normal cells, c-MYC is inhibited by HIF-1, but in cancer cells it interacts with HIF-1, further enhancing the Warburg effect by increasing the expression of glycolytic enzymes." (PMID 37332080, 2023). "However, the direct connections among these DUBs, MYC and cancer stemness are unknown." (PMID 36765885, 2023). "It is important for promoting the CSC phenotype, prompting de-differentiation of cancer cells to CSCs, as well as inducing the expression of pluripotent stem cell markers, OCT4, NANOG, SOX2, KLF4, c-MYC." (PMID 37614497, 2023). "MYC oncogene, which plays a critical role in CRC, is known to promote CD47 and PD-L1 expression on cancer cells through binding to their corresponding promoters." (PMID 37291116, 2023). "MYC is a major oncogene in GBM cells, and its amplification often enhances the malignant progression of cancer cells." (PMID 38093312, 2023). "In cancer treatments based on the CSC characteristics and inducing factors, MYC is a promising target for therapeutic molecules." (PMID 36765885, 2023). "Most genes were significantly correlated with gastric inflammation-cancer transformation, such as AKT1, EGFR, and MYC." (PMID 37964307, 2023). "Gain in 8q chromosomal arm and especially in 8q24 region harboring amplifications in CSMD3, MYC and ASAP1 genes, has been described in different type of cancers." (PMID 36357817, 2023). "MYC consists of 3 paralogs, C-MYC, N-MYC, and L-MYC, that are frequently deregulated driver genes in human cancers." (PMID 36959600, 2023). "Expression of PD-L1 in cancer cells is regulated by multiple signaling pathways, including transcription factors, such as STAT3, HIF1α and MYC." (PMID 37928424, 2023).